OR2AT4 (olfactory receptor family 2 subfamily AT member 4)
Description:
Olfactory receptor. Activated by the synthetic sandalwood odorant sandalore. Endogenous ligand is unknown (Probable). The activity of this receptor is probably mediated by G proteins which induce elevation of intracellular Ca(2+), a cAMP-dependent pathway and phosphorylation of MAPK1/ERK2, MAPK3/ERK1 and p38 MAPKs. Activation of OR2AT4 induces proliferation, migration, and re-epithelialization during wound-healing processes of keratinocytes. Stimulation of OR2AT4 by sandalore promotes hair growth by decreasing apoptosis and increasing production of the anagen-prolonging growth factor IGF1 as well as other pathways involving various kinases.
Synonyms: OR11-265
Tractability: Antibody: UniProt places it where antibodies can reach, with high confidence; its Gene Ontology location is reachable by antibodies, with high confidence; UniProt predicts a signal peptide or a membrane-spanning region.
Gene: Protein-coding gene on chromosome 11 (75,081,753 to 75,096,876, reverse strand). Ensembl gene ENSG00000171561.
Subcellular location: Cell membrane
Pathways (Reactome):
Sensory Perception: Expression and translocation of olfactory receptors; Olfactory Signaling Pathway
Gene Ontology:
Molecular function: olfactory receptor activity; G protein-coupled receptor activity
Biological process: positive regulation of ERK1 and ERK2 cascade; signal transduction; detection of chemical stimulus involved in sensory perception of smell; G protein-coupled receptor signaling pathway
Cellular component: plasma membrane; membrane
Genetic constraint (gnomAD): Loss-of-function variants: 7 observed, 11.66 expected, observed/expected ratio (o/e) 0.6, 90% interval 0.34 to 1.13. The upper end of that interval is the gene's LOEUF score, 1.13, which puts it in group 4 of 6, group 1 being the genes least tolerant of losing a copy. Missense variants: 354 observed, 409.51 expected, observed/expected ratio (o/e) 0.86, 90% interval 0.79 to 0.94. Synonymous variants: 145 observed, 161.93 expected, observed/expected ratio (o/e) 0.9, 90% interval 0.78 to 1.03.
Homologues: Orthologues: chimpanzee OR2AT4 (99% identical), macaque OR2AT4 (95% identical), dog OR2AT4 (88% identical), guinea pig OR2AT4 (87% identical), rat Olr35 (86% identical), mouse Or2at4 (86% identical), rabbit OR2AT4 (83% identical), pig OR2AT4 (55% identical). Paralogues in human: OR1F1 (42% identical), OR1N2 (41% identical), OR1L4 (41% identical), OR1L6 (41% identical), OR1N1 (41% identical), OR4E2 (41% identical), OR1J2 (40% identical), OR2A1 (40% identical), OR2A42 (40% identical), OR1J1 (40% identical), OR7A5 (40% identical), OR2A12 (40% identical), and 116 more.
Diseases named in the same sentence as OR2AT4 in open-access papers:
OR2AT4 is named in the same sentence as 7 diseases in open-access papers, as found by Europe PMC text mining. Sharing a sentence is not in itself a finding about the gene and the disease. The quoted sentences say what the papers report.
myelogenous leukemia (5 papers, 2016 to 2023). "In myelogenous leukemia, OR2AT4 promotes cell proliferation, apoptosis, and differentiation." (PMID 36779496, 2023). "Olfactory receptor family 2 subfamily AT member 4 (OR2AT4) was reported to regulate cell proliferation, apoptosis, and differentiation in human myelogenous leukemia." (PMID 31781505, 2019).
chronic myelogenous leukemia (2 papers, 2016 to 2017). "The activation of OR2AT4 by its agonist sandalore results in an enhanced proliferation of keratinocytes, whereas the activation of the same receptor in chronic myelogenous leukemia cells leads to a reduced proliferation and an induction of apoptosis." (PMID 29249973, 2017).
atherosclerosis (1 paper, 2025). A disease characterized by the build-up of fatty material and calcium deposition in the arterial wall resulting in partial or complete occlusion of the arterial lumen. "OR2AT4 could regulate the growth of human hair growth while Olfr2 could drive the production of atherosclerosis." (PMID 40523880, 2025).
leukemia (1 paper, 2016). A malignant (clonal) hematologic disorder, involving hematopoietic stem cells and characterized by the presence of primitive or atypical myeloid or lymphoid cells in the bone marrow and the blood. "With calcium-imaging, we characterized in greater detail the cell biological role of one OR (OR2AT4) in leukemia." (PMID 27551494, 2016). "Further preclinical studies are required to determine whether the OR2AT4 signaling pathway might be exploited for the treatment of leukemia." (PMID 27551494, 2016).
cancer (2 papers, 2016 to 2019). A tumor composed of atypical neoplastic, often pleomorphic cells that invade other tissues. "It has been observed that PSGR facilitates cancer cell proliferation, invasion, and migration, while OR2AT4 and OR51B4 hamper cancer cell behaviors." (PMID 31781505, 2019). "In contrast, the activation of OR2AT4 in K562 cells led to a complete inhibition of cancer cells proliferation." (PMID 27551504, 2016).
OR2AT4 also shares sentences with these, for which no sentence is quoted: psoriasis (1 paper); tumor (1).